IL2 (interleukin 2)
Diseases named in the same sentence as IL2 in open-access papers (continued):
Sharing a sentence is not in itself a finding about the gene and the disease.
tumor (continued). "The suicide gene therapy surgery adjuvant was combined with irradiated xenogeneic cells genetically modified to secrete human IL-2 and GM-CSF, and with an autologous or allogeneic formolized tumor cell vaccine plus interferon-β." (PMID 30759787, 2019). "In ACT, autologous TILs are initially isolated from an existing tumor mass, co-cultured with IL2 to grow ex vivo and subpopulations of these proliferating cells are tested in vitro against the patient’s original tumor." (PMID 31575023, 2019). "CIK cells are non-MHC-restricted T lymphocytes that, can be expanded ex vivo from a patients’ PBMCs, following stimulation with anti-CD3 antibody and IL-2, and can exhibit anti-tumor effects in vivo." (PMID 31151419, 2019). "In preclinical and clinical studies, IL2 is administered in combination with cancer vaccines to dramatically enhance their anti-tumor activity." (PMID 31291991, 2019). "It is a next-generation IL-2 fusion protein for efficient delivery of sumIL-2 not only to target EGFR positive tumor tissue but also to target CTL in TME for resulting in more effective tumor killing." (PMID 31462678, 2019). "During infection or an anti-tumor immune response, strongly activated CTLs in the presence of IL-12 and IL-2 will secrete exosomes quickly to promote the function of a robust population of low-affinity CTLs." (PMID 31275303, 2019). "An increase in N-(4-[18F]fluorobenzoyl)-interleukin-2 ([18F]FB-IL-2) uptake was shown when tumours were either irradiated or immunised, and further increase in uptake was observed when the treatments were combined, indicating a synergistic effect." (PMID 31656546, 2019). "By producing various cytokines including IFN-γ, tumor necrosis factor (TNF)-β, and interleukin (IL)-2, Th1 cells show a strong effect in repressing tumor growth, and IFN-γ possesses capabilities for anti-tumor effects and immunomodulation." (PMID 31038546, 2019). "The antitumor effects of Erb-sumIL2 were completely abolished in the presence of FTY720, confirming that tumor-infiltrating T cells are, in fact, necessary for tumor control by tumor-targeting mutant IL-2 therapy." (PMID 31462678, 2019). "Immunocytokines, particularly IL-2, have shown promising anti-tumor effects in several murine tumor models and a few have entered clinical trials." (PMID 31340613, 2019). "Another conditioning approach, by priming NK cells with tumor cells, has been shown to result in the activation of NK cells independently of IL-2 to generate NK cells able to lyse a variety of cancer targets." (PMID 31163679, 2019). "Another molecule that is nowadays largely used to study the tumour environment is interleukin-2 (IL2)." (PMID 31091813, 2019). "The authors reported a delay in tumor growth, an influx of lymphocytes and NK cells into the tumors, and, in the tumor microenvironment, reduced levels of the suppressive cytokines IL-10 and TGFβ, and increased levels of IL-2 and TNFα." (PMID 31588231, 2019). "Second, Tα1 fused with the Fc domain of human IgG4 plays anti-tumor effects in the 4T1 and B16.F10 tumor xenograft models by upregulating CD86 expression, secreting IFNγ and IL-2, and increasing the number of tumor-infiltrating CD4+ and CD8+ T cells." (PMID 31555601, 2019). "Results showed a further 26.50 ± 22.68% reduction in tumor growth in mice injected with IL-15 plus IL-2-treated DNTs compared to IL-2-treated DNTs." (PMID 30670085, 2019). "At the same time, IFN-γ and other lymphocytes, secreted by NK cells activated by IL-2 can further enhance the anti-tumor activities of monocyte macrophages and NK cells." (PMID 31334112, 2019). "Normally, the activation of CAR‐T cells in vivo will result in their killing of tumor cells accompanied with release of cytokines such as IL‐2, IFN‐γ, and TNF‐α." (PMID 31237116, 2019). "So, the cytotoxic activity of IL-2-expanded NKs from ICOS-KO mice is decreased against tumor cells; which is remarkable when target cells expressing high levels of ICOS-L are used." (PMID 31283790, 2019).
tumor (continued). "In this line, the combination of IL-2 with anti-CD40 antibody was effective on cancer growth control in two different mouse tumor models by inducing M-MDSC elimination trough Fas-mediated apoptosis." (PMID 31447834, 2019). "Neo-epitope-specific CD8+ T cells displayed high expression of other effector molecules, such as TNF-α, granzyme B and IL-2, which is consistent with anti-tumor cytotoxic activity." (PMID 31562311, 2019). "We evaluated the optimal concentration of IL-2 required to inhibit the proliferation of tumour cells." (PMID 31662754, 2019). "Patients were treated with either dacarbazine or temozolomide, alkylating agents that inhibit DNA synthesis, or high dose interleukin-2 (IL-2), a recombinant analogue that acts to stimulate immune activity against the tumor." (PMID 35582566, 2019). "A vaccine strategy based on XCL1- and IL-2-secreting neuroblastoma cells enhanced T-cell infiltration and resulted in complete or partial tumor remission in vaccinated patients." (PMID 30979057, 2019). "When transferred into mice with leukemia, IL-21-treated CARs had improved tumor control compared to those treated with IL-2 ex vivo." (PMID 30842774, 2019). "In this strategy, NK cells are modified to produce cytokines such as IL-2 and IL-15 which increase their survival capacity and proliferation and promote anti-tumor activity in vivo." (PMID 30823602, 2019). "A combination of TKD/IL-2-stimulated NK cells with anti-PD-1 antibodies resulted in 1.5-fold increase of anti-tumor cytotoxicity of lymphocytes that indicates the synergistic effect of both therapeutic concepts." (PMID 30967859, 2019). "As a further hallmark of T-cell activation upon tumor lysis, a number of cytokines were released into culture supernatants, including IFN-γ, TNF, IL-6, and IL-2." (PMID 31293575, 2019). "There are multiple conditions within the tumour microenvironment that will contribute to this NK cell dysfunction, including low concentrations of glucose and also low levels of IL2." (PMID 31595191, 2019). "The adoptive transfer of NK cells from healthy donors showed the killing of stem-like and differentiated tumor cells upon activation with IL-2 and IL-15." (PMID 30841635, 2019). "Expression levels of perforin, granzyme B, IFN-g, TNF-a, and IL-2 in CD8+ tumor-infiltrating lymphocytes (TILs) were significantly lower than those in CD8+ T cells of peripheral blood." (PMID 30682105, 2019). "The combination of drug therapy with NK cell stimulating cytokines (IL-2, IL-12, IL-15, and IL-21) or immunomodulatory drugs (IMiDs) can enhance NK cell-mediated tumor killing." (PMID 30823602, 2019). "The flavonoids of Hippophaerhamnoides L (TFH) isolated from berries of sea buckthorn up-regulated the levels of IL-1α, IL-2, IL-7, IL-15 etc. to activate NK cells and its cytotoxicity against tumor cells K562." (PMID 31138762, 2019). "There is a report that activation of NK cells with IL-2 and IL-12 increased perforin binding and subsequent lysis of tumor cells." (PMID 31426763, 2019). "Fresh tumor tissues from 25 PDXs were tested for TIL culture with supplemental human IL-2 in the culture medium." (PMID 30477533, 2018). "This process leads to phagocytosis of the targeted tumor cells and cell death by pro-apoptotic cytokines such as IL-2, IL-12, and TNF-α." (PMID 30103457, 2018). "Further study revealed tumor regression due to intensified response of T lymphocytes, implemented through administration of interleukin 2 (IL-2) or autograft of tumor-infiltrating lymphocytes (TILs)." (PMID 29589142, 2018). "Sensitivity to immunotherapeutic intervention in this tumour type was already known from the clinical responses of some RCC patients to IL-2 treatment." (PMID 29875199, 2018). "This triple combination therapy includes external beam radiation to the tumor, intratumoral injection of a tumor-specific immunocytokine (anti-GD2 mAb linked to IL2) and anti-CTLA-4." (PMID 30400822, 2018).
tumor (continued). "Previous studies showed that IFN-γ, TNF-α, and IL-2-expressing CD8+ T cells are instrumental in anti-tumor immune response." (PMID 30619765, 2018). "Preclinical studies have shown that combining IL-2 or IL-15Rβγ agonists with anti-PD-1 monoclonal antibodies can improve anti-tumor responses." (PMID 30060526, 2018). "TILs are prepared from infiltrated lymphocytes of resected tumor specimen and expended in the presence of IL-2." (PMID 30333226, 2018). "We modeled IL-2 as an anti-tumor and pro-tumor cytokine because IL-2 can stimulate NK cells, CTL and Tregs." (PMID 35847834, 2018). "We found a negative correlation between IL-2 and tumor size confirming the necessity of IL-2 to protect from tumor development." (PMID 30687269, 2018). "Inhibiting systemicautophagy during interleukin 2 immunotherapy promotes long-term tumor regression." (PMID 30400835, 2018). "These tumor-derived exosomes also increased the secretion of the pro-inflammatory cytokines IL-1β, IL-6, and IL-10, and decreased the release of IFNγ, IL-2, and IL-17, both in CD4+ and CD8+T cells." (PMID 29515996, 2018). "Although NK cells can be converted into MDSCs in allograft tumor models, this conversion is inhibited by the presence of IL-2." (PMID 29690614, 2018). "Pre-activation of NK cells with IL-2 or IL-12, IL-15 and IL-18 results in the generation of NK cells efficient to target and kill tumor cells." (PMID 30323819, 2018). "Although the IC50 values of cis-3M-RES for malignant tumor cells tested were 0.07-0.17 μM, those for unstimulated human peripheral T cells and IL-2-dependent proliferation of PHA-stimulated peripheral T cells were >10.0 and ∼0.23 μM, respectively." (PMID 29435156, 2018). "The involvement of NK cells in the therapeutic effect of IL-2 immunocytokine has been further confirmed in targeting the tumor stroma with the F16-IL-2 immunocytokine." (PMID 30619269, 2018). "From a clinical and therapeutic point of view, it is crucial to know the capacity of tumor NK cells to be rescued in their antitumor function by using activating cytokines such as IL-2." (PMID 29713652, 2018). "One factor in this pathway is IL-2 secretion: increased IL-2 secretion results in activated macrophages and tumor lysis directly from CD8+ T-lymphocytes." (PMID 29996539, 2018). "Here, we describe a new form of IL-2 immunotherapy through delivery of a cell membrane-bound IL-2 by tumour-targeted oncolytic vaccinia virus." (PMID 30410056, 2018). "In striking contrast, Lipo-αCD137/IL-2-Fc therapy greatly suppressed tumor growth, with negligible lung signal detected through ~25 days, as monitored by IVIS bioluminescence imaging." (PMID 29295974, 2018). "The tumor secreted serum IL-2 level was downregulated in the oncoVV-HddSBL group compared to the oncoVV group." (PMID 29701680, 2018). "IL-2 is critical to the activation, growth, and survival of T cells and NK cells, and maintains the delicate balance between auto-immunity and anti-neoplasm surveillance." (PMID 30250191, 2018). "Early models of ex vivo expansion focused on tumor-infiltrating lymphocyte models, where T cells are expanded to large numbers with high dose IL-2 and anti-CD334." (PMID 30479831, 2018). "Combined administration of MB and IL-2 into Meth-A sarcoma-bearing mice resulted in significant tumor inhibition and complete tumor regression in 70% of treated mice." (PMID 29666781, 2018). "Tumor priming and IL-2 stimulation of patient-derived NK cells resulted in similar levels of cytotoxicity, but distinct NK cell phenotypes." (PMID 30761160, 2018). "We previously conducted a phase I clinical study using autologous tumor lysate-pulsed, monocyte-derived, mature DC vaccinations combined with low-dose IL-2 in patients with stage IV malignant melanoma, which showed that the treatment was safe." (PMID 29293510, 2018).
tumor (continued). "Mechanistically, tumor infiltrating lymphocytes (TILs) are collected and genetically engineered into a patient’s microenvironment along with systemic interleukin-2 (IL-2) to stimulate their survival and expansion." (PMID 29473044, 2018). "Intratumoral injections of recombinant NDV expressing IL-2 elicited immune reaction and induced dramatic reduction in tumor growth, resulting in complete and long-lasting remission in the mice bearing colon carcinoma or hepatoma." (PMID 29857493, 2018). "The IL-2 expression leads to a favourable immune profile in the tumour microenvironment, which correlates with the antitumour response." (PMID 30410056, 2018). "mPD1-Fc-OX40L demonstrated high affinity binding to mPD-L1 and mOX40 targets across in vitro binding assays and displayed biological activity as evidenced by increased IL2 release in tumor/T cell co-culture and SEB assays." (PMID 30563566, 2018). "Many studies have shown that MSCs engineered to express anti-tumour cytokines, such as interleukin-2 (IL-2), interferon-beta (IFN-β), TRAIL, and IL-15, are able to deliver these ligands directly to the tumour site and to efficiently induce tumour regression." (PMID 30060445, 2018). "This is supported by studies from our laboratory showing that CD8+ T cells are important anti-tumor effector cells during IL-2/CD40 treatment, and other studies showing that DCs, CD8+ T cells and IFN-γ are required for IL-2/CD40-mediated tumor regression." (PMID 30560130, 2018). "In contrast, ibuprofen treatment during involution increases the abundance of mature macrophages, T cells, and tumoral cytokines (IL-2, IL-12, TNFa) supportive of Th1 and anti-tumor immunity." (PMID 30285905, 2018). "Nevertheless, expression of IL-2 is declined in splenocytes and increased in tumor infiltrating lymphocytes, inversely." (PMID 30619765, 2018). "The expression levels of IL-2 were significantly higher in the ARG-V groups compared to the tumour model group, particularly in the middle and high dose groups (P < 0.01) while it obviously decreased in the CTX group." (PMID 29459629, 2018). "TC1 primary tumour cells had higher levels of several immunostimulatory factors (IFNγ, IL-2, TNFα), including antigen presenting molecules (H2-K1) as compared to the A9 metastatic tumour cells." (PMID 29440650, 2018). "This new IL-2 variant, named NKTR-214, has shown promising anti-tumor responses and decreased toxicity and it is now finding its way to the clinic." (PMID 30319612, 2018). "The whole blood of patients with cancer was also exposed to IL-2, IL-15 and IL-21 in culture, which we have previously reported to have a pronounced effect on amplifying tumor-directed T-cell responses." (PMID 29970101, 2018). "Following the third treatment on day 10, mice administered Lipo-αCD137/IL2-Fc already showed a significant reduction of tumor burden in the lung comparing to control Lipo-IgG and untreated groups." (PMID 29295974, 2018). "For example, IL2 is a cytokine, which plays a role in the activation of the immune response against tumor cells." (PMID 29868476, 2018). "As previous studies from our laboratory have shown that CD8+ T cells and perforin-associated effector function are important for IL-2/CD40-mediated tumor regression in young mice, this likely contributes to poorer tumor responses by elderly mice to IL-2/CD40." (PMID 30560130, 2018). "IL-2’s high potency for activation of CD4+ regulatory T cells (Tregs) that suppress T cell-mediated tumor killing responses further reduces its therapeutic window." (PMID 30400822, 2018). "Of note, IL-2 was critical for the profound proliferation of IL-12/15/18 pre-activated NK cells, their anti-tumor activity and persistence in several organs such as blood, spleen, liver, and lung after adoptive transfer." (PMID 30546366, 2018). "On one hand, cytokines such as interferons (IFN-γ, IFN-α) and interleukins (IL-2, IL-12) show anti-tumor capacity." (PMID 30424010, 2018).
tumor (continued). "The cells displayed pro-inflammatory (IL-2, IL-8, and TNFα) and anti-inflammatory (IL-4 and IL-10) activities IL-2, IL-4, and IL-8 can promote the proliferation and survival of tumor cells by means of autocrine/paracrine signaling pathways." (PMID 29495627, 2018). "As an innate cytokine in the immune system with essential and wide spectrum of immunological functions, IL-2 has long been used for cancer treatment alone and has shown great tumor regression." (PMID 29473044, 2018). "This treatment involves TIL harvest at the time of tumor resection, expansion and stimulation with IL-2, and reinfusion of stimulated TILs into the body." (PMID 30568917, 2018). "Fresh tumor from primary (P) and peritoneal metastasis (PM) cancer lesions and colon tissue (C) were cultured in medium containing IL-2, IL-15 and IL-21." (PMID 30400835, 2018). "Treatments with NK-activating cytokines, IL-12, IL-18, or a mutant form of IL-2 (the “superkine” called H9), restored effector functions of MHC-I-deficient tumor-infiltrating NK cells with impaired signaling downstream of activating receptors." (PMID 30719024, 2018). "From the same cases, fresh tumor tissue was cultured in medium containing IL-2, IL-15 and IL-21 to cultivate TILs, and percentage of TCR gamma-delta T-cells (CD3+ TCR γδ+) and NK cells (CD3- CD56+ CD16+) was analyzed by flow cytometry (FC)." (PMID 30400835, 2018). "Accordingly, a correlation between the expression level of CD103 on tumor-specific T-cell clones, stimulated in vitro with IL-2 and irradiated autologous tumor cells, and their capacity to kill autologous E-cadherin+ tumor cells was observed." (PMID 30180905, 2018). "Patients derived (1 VHL-WT, 3 VHL-MUT)-IL-2 activated NK cells were cultured in the presence of RCC cell lines or freshly isolated autologous tumor cells." (PMID 30514329, 2018). "Previously, IT IL-2 was required to activate and sustain tumor-specific lymphocytes generated from RT of B78." (PMID 30400822, 2018). "The cells produced cytokines such as IL-1B, IL-2, and IL-8 and displayed significant tumor-killing capacity." (PMID 29707004, 2018). "During the dissection of the mice, the investigator found that the boundaries between the normal and tumor tissues were unclear in the control and wild-type IL-2 groups." (PMID 30250191, 2018). "In general, effector cells rejected the tumor cells, accompanying with cytokine release, including IL-2, TNFα, IL-6, and IFNγ." (PMID 30103775, 2018). "This was followed by the elucidation of the role of T cells in anti-tumour immune responses which led to the clinical use of the T-cell growth factor interleukin-2 (IL-2)." (PMID 29875199, 2018). "Because of the well-known role of IL-2 in NK cell proliferation and the cytotoxic activities of these cells on tumor development, we assessed the systemic expression of NK cells." (PMID 30687269, 2018). "When Vγ9Vδ2 T cells are activated by phosphoantigen or aminobisphosphonate and the culture medium includes IL-2, IL-15, or other cytokines, the resulting cells demonstrate potent tumor cell cytotoxicity." (PMID 29937769, 2018). "Elevated IFN-γ expression by CD11c+ cells, and increased CD25 expression by CD8+ T cells suggests these cells are more activated with increased effector function and contribute to IL-2/CD40-induced slowing of tumor growth." (PMID 30560130, 2018). "IL-2/CD40 reduced CD25 and IFN-γ in tumor-associated CD4+ T cells in both age groups alongside reductions in the regulatory markers CD73 and CTLA-4." (PMID 30560130, 2018). "Taken together, our data demonstrates that vvDD-IL-2-FG and vvDD-IL-2-RG effectively maintains the IL-2 in the tumour microenvironment, and are, therefore, far safer than vvDD-IL-2." (PMID 30410056, 2018). "Liposomal IL-2-Fc showed a ~50% increase in tumor accumulation comparing to that of free IL-2-Fc at 4 h, while accumulations of liposomal and free IL-2-Fc were comparable at 24 h." (PMID 29295974, 2018).